CD86 (CD86 molecule)
Diseases named in the same sentence as CD86 in open-access papers (continued):
Sharing a sentence is not in itself a finding about the gene and the disease.
tumor (continued). "Expression of the DC markers MHCII and CD86 on NCsh and CRIG-Ish tumor TIDCs was downregulated compared with the expression of both markers on splenic DCs, CRIG-Ish tumor TIDCs exhibiting significantly lower expression levels of MHCII and CD86 than those of NCsh tumor TIDCs (n = 6)." (PMID 31088527, 2019). "While DMXAA treatment did not significantly increase the frequency of CD103+ DCs within the tumor (data not shown), there was a profound and significant increase in CD86 expression on both CD103+ DCs and CD11b+ DCs in tumors treated with STING agonist." (PMID 31036082, 2019). "In addition, the co-stimulatory molecule CD86 was upregulated in both CD11c+MHC-IIhiCD26+XCR1+CD172a− cDC1 and CD11c+MHC-IIhiCD26+CD172a+XCR1− cDC2 in the tumor-draining lymph node." (PMID 31694706, 2019). "Interestingly, Trapoxin A treatment led to the up-regulation of costimulatory and adhesion molecules (CD80, CD86, HLA-DR, HLA-ABC, and ICAM-1) in AML cells, inducing tumor immunity." (PMID 31739588, 2019). "Furthermore, the percentages of CD86+MHC IIhi mature DCs and antigen- specific immune responses in the TME were higher in the tumor-bearing hosts treated with combinational regimens." (PMID 31052575, 2019). "Two signals are needed to induce T cell activation: binding of the MHC receptor with the tumour antigen to the TCR and binding of CD80/CD86 (also known as B7-1 or B7-2), which is primarily expressed on antigen presenting cells (APCs), to CD28 expressed by T cells." (PMID 31561518, 2019). "Treatment of CTLA-4 expressing tumor cell lines with recombinant forms of the CTLA-4 ligands CD80 and CD86 induced caspase-8-dependent apoptosis and the level of apoptotic tumor cells was reduced by soluble CTLA-4 and anti-CTLA-4 single-chain variable fragment antibodies." (PMID 29682176, 2018). "Unlike CD80 and CD86, the PD-1 ligands (PD-L1 and PD-L2) are not only expressed by APCs, but also by other immune cell types as well as tumor cells." (PMID 29617360, 2018). "CD40 and CD86 expression were comparable in DCs from tumour-bearing mice regardless of Y27632 treatment." (PMID 29867097, 2018). "In fact, the dysregulated expression of both CD80 and CD86 could negatively affect CTL and Treg functions allowing tumor spread." (PMID 30123257, 2018). "Treatment of human breast cancer with dexosomes resulted in incorporation into tumors and subsequent expression of dexosome immunostimulatory molecules (e.g., CD86, CD81, MHCI/II + tumor antigen) on tumor cell surfaces, thus boosting tumor immunogenicity and T-cell engagement." (PMID 30191140, 2018). "The TC-1 and MC32 cells displayed no CD80, CD86 or CD40 surface expression, supporting the notion that CD80 is not directly associated with IFN-γ production and tumor progression." (PMID 28460461, 2017). "In addition, post-NAC patients whose tumours had a GPR had a significantly increased expression of HLA-DR, CD40, CD86, and the LNHR CD197." (PMID 28913366, 2017). "However, only SN of the irradiated tumor cells induced a significant higher increase in the percentage of migrated mDCs showing enhanced expression of the activation markers CD80 and CD86 compared to mock treated and medium controls." (PMID 28337197, 2017). "Importantly, knockdown of LSD1 demonstrates strong anti-tumor effects in THP-1 (MLL-AF9) xenograft model, accompanied with increased CD11b and CD86 expression." (PMID 29156705, 2017). "We observed, that P2Et-treated mice had higher numbers of spleen conventional DCs (CD45+, CD220−, CD11c+) with increased surface expression of co-stimulatory molecules such as CD86, CD40, MHCII and CD70, suggesting that in vivo P2Et treatment actually enhances the immunogenicity of tumor cells." (PMID 27253407, 2016). "Moreover, the percentage of CD11c, CD86 and MHC II co-expression on MDSCs in cryo-thermal group was significantly higher than that of the tumor-bearing control group." (PMID 27256519, 2016).
tumor (continued). "The current study demonstrates significantly decreased expression of PD-1 and CTLA-4 on tumor-infiltrating CD8+ T cells and decreased expression of their ligands (PD-L1 and CD86, respectively) on dissociated tumor cells from animals maintained on the KD when compared to control animals." (PMID 27178315, 2016). "While activation of inflammatory macrophages (CD86/LYSC) in other tumors improved OV anti-tumor efficacy, inflammatory macrophage activation inhibited oncolytic herpes simplex virus (oHSV) anti-tumor efficacy in glioma in part through the TNFβ-mediated inhibition of virus replication." (PMID 28536380, 2016). "The Carthamus tinctorius L., one of AVS073′s components, was reported to promote the expression of maturation markers (CD80, MHC class I and II) in mouse bone-marrow-derived DCs and maintained the high profile of maturation markers (CD80, CD86, MHC class I and II) in tumor antigen pulsed-DCs." (PMID 27899095, 2016). "This increase is specific since the percentages of F4/80+CD86+ cells present in the liver of tumor bearing mice treated with OGNVs/Ctrl alone were no different from those treated with OGNVs-miR18a." (PMID 27028860, 2016). "In contrast, the preoperative serum levels of CTLA‐4, B7‐H3, CD28, CD80, and CD86 were not correlated with tumor biological characteristics in this study." (PMID 27292320, 2016). "Neither a CD86-interfering antibody nor the isotype control affected numbers of GrBhi CTLs or tumor spheroid killing." (PMID 25871398, 2015). "CD86 expression was not regulated by LPS and blocking of CD86 neither changed GrBhi CTL numbers nor rescued tumor spheroid sizes." (PMID 25871398, 2015). "The changes to iMoDC surface phenotype are likely to be tumor-driven, as exposure to Met5A cells did not alter the percent of CD1a+, CD86+ or CD80+ iMoDCs, nor did it alter surface expression levels (MFIs) of CD86 or CD80 on iMoDCs, relative to DCs only." (PMID 25886502, 2015). "T-cell activity is regulated by antigen-presenting cells (APCs), which can either promote activation of tumor-specific T-cells or induce antigen-specific peripheral tolerance in absence of co-stimulatory signals such as CD86." (PMID 26107883, 2015). "Absolute numbers of CD86− mature CD8α+ non-plasmacytoid DCs increased following tumor inoculation in mice at ST but not TT." (PMID 24575090, 2014). "Interestingly, we found that the T cell costimulatory molecules CD80 and CD86 and the mature molecule CD83 were substantially upregulated on the tumor-activated γδ T cells, along with the obvious increased expression of HLA-DR (n = 9)." (PMID 24741609, 2014). "Therefore, a possible mechanism for the APC-like behavior of tumor-activated γδ T cells is that these cells are loaded with tumor components for a brief period, during which they process and express costimulatory molecules CD80/CD86." (PMID 24741609, 2014). "The percentage of CD86− mature CD8α+ non-plasmacytoid DCs decreased at ST but not TT following tumor inoculation." (PMID 24575090, 2014). "At ST, there was an increase in absolute number and a decrease in the percentage of CD86− mature CD4+ non-plasmacytoid DCs in response to tumor, but no significant changes were observed at TT." (PMID 24575090, 2014). "We did see a reduced percentage of CD86+ mature CD4+ non-plasmacytoid DCs at ST but not at TT following tumor inoculation." (PMID 24575090, 2014). "In the present study, we demonstrated that CTLA4Ig promotes anti-tumor immunity via enhancement of NK cell cytotoxicity to tumor cells and that ligand of CD86, but not CD80, on NK cells by CTLA4Ig is critically involved." (PMID 24349559, 2013). "Although studies of expression levels of CD86, MHC class I, and MHC class II are important to evaluate the activation levels of DCs in anti-tumor immune responses, other activation markers for DCs might exist, such as ICAM-1 or B7." (PMID 23865808, 2013).
tumor (continued). "To validate the role of GDF-15 in tumor progress, we used a GDF-15 polyclonal antibody to block the GDF-15 induced maturation and the result revealed that the antibody abolished the effect of GDF-15 on inhibiting CD83, CD86 and HLA expression on mDCs in vitro." (PMID 24236027, 2013). "Using tumor cells rather than IL-15 and IL-2 as stimulators also induced significant expression of CD86, but not CD80, on NK cells, both in vitro and in vivo." (PMID 24349559, 2013). "On the contrary, tumors that are induced to express costimulatory molecules that activate T cells, such as B7.1 (also known as CD80), and B7.2 (also known as CD86) are cleared by the immune system and thus may be used as a strategy to promote tumor immunity." (PMID 23533456, 2013). "Based on the fact that CTLA4Ig binds with high affinity to CD80/CD86, we hypothesized that CD80 or CD86 might play in role in the ability of CTLA4Ig to enhance NK cell functions against tumor metastasis." (PMID 24349559, 2013). "Moreover, we did not observe any difference in the expression of 5 additional markers that are relevant for the interaction of lymphocyte and tumor cells (PD-1, CD80, CD86, PD-L1 and PD-L2)." (PMID 23284620, 2012). "The efficient stimulation of tumor-specific T lymphocytes by DCs requires the presentation of tumor-derived epitopes on MHC class I and II molecules together with second signals (costimulatory molecules CD80, CD86, CD40) and proinflammatory cytokines such as IL-12 or TNF-α." (PMID 22110524, 2011). "Interestingly, treatment with each of the four tumor exosomes tested all resulted in the down-regulation of MHC class II molecules (I-Ab) and CD86, suggesting that in the presence of tumor exosomes the spontaneous maturation of DCs can be inhibited." (PMID 21829629, 2011). "Indeed, treatment with tumor exosomes down-regulated the expression of MHC class II molecules and CD86 on BMDCs and induced TGF-β1 production by DCs in culture." (PMID 21829629, 2011). "Indeed, DCs detected in tumor tissue or local tumor draining lymph nodes (TDLN) of cancer patients display an immature phenotype defined by low expression of CD80, CD86 or CD83, and altered APC function." (PMID 20976125, 2010). "At day 5, U-251 tumor cell lysate was added to the generated immature DCs and by day 6, cell started exhibiting morphological changes that were accompanied with the further changes in the expression of DCs' phenotypical markers such as CD83, CD86, HLA-DR." (PMID 20195476, 2010). "When pooled serum (n = 5 for each group) from naïve mice, tumor-bearing mice, mice treated with PC61 alone, or mice treated with two weekly injections of the vaccine cell-line AGN2a-CD80/CD86 alone was used to screen the cDNA library 0, 0, 0, or 5 unique clones, respectively, were identified." (PMID 17397536, 2007). "In addition, targeting of CD86 and/or CD80 in experimental tumours, even of low immunogenicity, was found to promote antitumour CTL responses." (PMID 12771917, 2003). "In a BMDC-splenocyte-HCC co-culture system, GOx-DOX-LGPsignificantly enhanced dendritic cell maturation (CD86+ MHC-II+ in CD11c+) and CD8+ T-cellactivation and proliferation, as evidenced by increased granzyme Band Ki67 expression, culminating in enhanced tumor cell lysis." (PMID 41493269, 2026). "Additionally, in vivo experiments using syngeneic transplantation of CT26 cells in mice revealed that combining RSL3 with an HIF-1α inhibitor markedly enhanced tumor suppression and metastasis prevention, concomitant with increased intratumoral infiltration of CD8+ T cells and CD86+ macrophages." (PMID 41945999, 2026). "The co-expression network suggests that by influencing the interplay of CD86 and neural signal features such as LYN, PLXNC1, and DOCK10, it may mediate the interaction between neural signals and M1 macrophages, thereby affecting anti-tumor activity." (PMID 41147013, 2025).
tumor (continued). "KCNN4 has been shown to have positive correlations with several costimulatory molecules (CD276, CD40, CD70, CD80, CD86), immune signaling receptors (IL2RA, MICB, NT5E), and multiple TNFRSF family members, suggesting its involvement in immune modulation, inflammation, and tumor‐immune interactions." (PMID 40952239, 2025). "FC analysis of tumor innate immune cell populations indicated that at day 6 after the first treatment, both VVL-TD-RFP and VVLΔTKΔN1L treatments significantly increased the proportion of DC, CD86+ DC, and major histocompatibility complex (MHC)-II+ DC compared with PBS." (PMID 40350204, 2025). "In contrast, CD86 expression in the tumor stroma had no measurable impact on this interval." (PMID 40510346, 2025). "The expression levels of ALG3 in tumor cells and stromal cells were positively correlated with the abundance of CD4+ FOXP3+ regulatory T cells (Tregs), CD3+CD4+ T cells and PD-L1, whereas they were negatively correlated with the abundance of CD8+ T cells and CD68+CD86+ macrophages." (PMID 40475760, 2025). "Notably, anti-CD80/CD86 as a single agent or in combination with radiation also resulted in an overall decrease in CD4 T cells as a percent of live cells in the tumor, without impacting CD8 T cell proportions." (PMID 41417245, 2025). "In addition, CD163 was associated with hormone receptor-negative breast cancer, while CD86 correlated with higher tumor grade." (PMID 40510346, 2025). "Additionally, PD-L1 interacts with B7 (CD80 and CD86), producing negative signals on T cells and inhibiting anti-tumor immunity." (PMID 39114662, 2024). "Importantly, following CD86 blockade, the frequency of proliferating (Ki67+) CD8+ T cells significantly increased in the tumor, while combined CD86 and PD-1 blockade increased this cell population in both the TdLN and tumor." (PMID 38349740, 2024). "Additionally, the expression of M1 macrophage markers CD86 and CD80 in tumor tissues surpassed that in adjacent tissues, while the expression of M2 macrophage markers CD163, CD206, and Arg-1 in tumor tissues was also higher than in adjacent tissues (p<0.05, p<0.01)." (PMID 39531417, 2024). "Moreover, we determined that the level of CD86 expression was higher on ZsG+ cDC from BH treated TDLN compared to sham controls, yet we did not observe a proportional increase in CD86 expression as cDC acquired more tumor antigen after BH." (PMID 38389838, 2024). "After tumor ablation, the remaining tumor debris was released from the tumor site to the 3D scaffolds stimulating the vaccine-like effect of R837 which promoted the recruitment and maturation of dendritic cells (DCs), as expressed by the percentage of mature DCs (CD11c+, CD80+, CD86+)." (PMID 38791452, 2024). "After administering the in situ gel vaccine with or withoutanti-PD-1 antibody in the gel (Dox-cGAMPnp@Gel or aPD1-Dox-cGAMPnp@Gel),we found that the number of tumor-infiltrating DCs did not changein either model, but there was a significant increase in their activation (CD86+MHCII+)." (PMID 39405469, 2024). "Since tumor-infiltrating lymphocytes (TILs) and macrophages can be detected in the tumor tissue of patients with cSCC and BCC, elucidation of CD28 and CD86 expression within the TME may be crucial." (PMID 39329753, 2024). "Interestingly, we observed that CD86 blockade significantly reduced the RT-induced eTreg population in the non-TdLN, TdLN, and tumor." (PMID 38349740, 2024). "However, the formation of the tumor microenvironment independent of HPV also reduced CD86 expression, indicating that there is a failure in antigen presentation as a tumor escape mechanism, which is a target for immunotherapeutic strategies." (PMID 39493451, 2024). "The density of CD86 immunolabeled tumor cells showed no group-related differences." (PMID 38962703, 2024).
tumor (continued). "However, the interaction of CD86 with CTLA-4, a regulatory receptor also present in some T cells, can suppress the activation of these effector cells, contributing to immunosuppression and allowing the tumor to evade immune surveillance." (PMID 38791312, 2024). "Immunohistochemical staining for CD80 and CD86 (activated dendritic cells markers) was performed in representative cases, which showed strong positivity at the tumor stromal interface in activated tumors but not in suppressed tumors, supporting the RNA-Seq findings." (PMID 39108491, 2024). "APOC1 is primarily expressed in tumor cells and macrophages and shows a positive correlation with the expression of genes such as CD68, CD86, CD163, CXCL17, CXCL8, and IL-10, suggesting that APOC1 may promote tumor progression by influencing macrophage polarization." (PMID 39877420, 2024). "The more infiltration of CD86 + in non-pCR patients, the more residual tumor in primary site." (PMID 38802821, 2024). "In the present study, while CD86 and PD-L1 were expressed at constant levels throughout tumor growth and regression phases, the level of CD80 positive cells was shown to decline during the latter pointing to a CD80 mediated effect on tumor immune evasion in CCH." (PMID 38962703, 2024). "After demonstrating in vivo efficacy of our CAR/CCR construct in the treatment of CD19/CD80/CD86-positive tumors, we next raised the question whether second-line treatment with CAR (2nd Gen) or CAR/CCR T cells can increase the survival of tumor-relapsed mice after CAR T cell treatment." (PMID 38340727, 2024). "The B7 immune checkpoint superfamily includes B7-1 (CD80), B7-2 (CD86), B7-H1 (PD-L1, CD274), PD-L2 (PDCD1LG2), B7-H3 (CD276), B7-H4 (B7-x, VTCN1), and the inducible costimulator ligand (L-ICOS, CD275), which act as ligands on the surface of tumor cells or antigen-presenting cells." (PMID 36983005, 2023). "While the frequency of infiltrating antigen presenting cells in the tumor was not significantly impacted by the therapies, the costimulatory molecule CD86 was upregulated in CD103+ DCs after PLE‐IL‐12‐NPs or free IL‐12 therapy, suggesting an enhanced activation of those cells." (PMID 36925719, 2023). "Notably, IDHmt specimens exhibited significantly enhanced CD86+ GAMs, while IDHwt samples showed markedly increased CD163+ GAMs, indicative of M1‐ and M2‐like phenotypes, respectively, in these two distinct subtypes of tumor entities." (PMID 37166058, 2023). "As costimulatory molecules, levels of CD80 and CD86 of DC2.4 in the LEH-CSPC + laser group showed significant enhancements compared with those of LEH-CSPC alone, indicating the importance of the PDT effect on antigen release from tumor cells and subsequent DC maturation." (PMID 37223478, 2023). "Interestingly, and in line with the stress-ligand results, we only observed a cisplatin-dependent rise in PD-L1, CD86, CD155, and Gal9 surface abundance on CHLA-136 tumor cells (1.7-, 2.8-, 1.6-, and 1.3-fold increase; p = 0.0222, p < 0.0001, p < 0.0001, and p = 0.0093, respectively)." (PMID 36765861, 2023). "The expression of PD-L1 on tumor cells contributes to the prediction of clinical efficacy of ICI in some tumor types, such as non-small cell lung cancer, which take advantage of the crucial roles played by the PD-L1/PD-1 and CTLA4/CD80/CD86 axes in the evasion of immune surveillance." (PMID 37893096, 2023). "In the tumor, XCR1 detection was also decreased in mice treated with the high dose of the XCR1Ab-IFNL53A fusion (10 mg/kg) compared to the isotype control, which correlated with a significant gain in IFN activity in cDC1s, based on greater PD-L1 and CD86 expression." (PMID 37942313, 2023). "However, tumor cells express positive costimulatory molecules, such as CD80 and CD86, at reduced levels that are insufficient to provide an effective second signal for T-cell activation, and thus, cannot effectively induce the anti-tumor immune response, generating immune tolerance instead." (PMID 37138865, 2023).